MYCN (MYCN proto-oncogene, bHLH transcription factor)
Diseases named in the same sentence as MYCN in open-access papers (continued):
Sharing a sentence is not in itself a finding about the gene and the disease.
neuroblastoma (continued). "LncRNA SNHG1 is up-regulated by MYCN amplification and could be a potential prognostic biomarker for neuroblastoma intervention in patients." (PMID 31269941, 2019). "Neuroblastoma patients with overexpressing MYCN and MYCN protein had lower survival rates." (PMID 31338261, 2019). "Amplification of MYCN was identified in neuroblastoma cell lines and then in untreated tumors." (PMID 30754710, 2019). "MYCN-amplified (MNA) neuroblastoma is an aggressive neural crest-derived pediatric cancer." (PMID 31624245, 2019). "Nevertheless, the finding here, show that loss of Casp2 affects several components regulating the Wnt signaling pathway in neuroblastoma, that could impact neuronal differentiation and possibly neuroblastoma onset in Th-MYCN/Casp2−/− mice." (PMID 30670683, 2019). "mir-17~92 dysregulation is common in MYCN-amplified neuroblastomas." (PMID 31616462, 2019). "In MYCN-amplified neuroblastoma cells, higher MRE11 expression predicts poorer prognosis." (PMID 31767017, 2019). "Furthermore, we elucidated the upstream epigenetic repressive regulation of ELOVL2 through MYCN and PRC1 complex-mediated histone ubiquitination in MYCN-amplified neuroblastoma." (PMID 31856871, 2019). "Consistently, the most malignant neuroblastoma contains amplification of MYCN." (PMID 31396265, 2019). "For human neuroblastoma, the amplification of the MYCN(V-myc myelocytomatosis viral-related oncogene, neuroblastoma derived [avian]) oncogene occurs in 20–25% of the patients, and the degree of amplification is associated with advanced stage and poor prognosis." (PMID 30741995, 2019). "Therefore, MYCN amplification is a significant predictor of poor clinical outcome in neuroblastoma patients." (PMID 31396265, 2019). "Furthermore, neuroblastomas with high expression of MycN or c-Myc have been shown to exhibit enlarged nucleoli." (PMID 30542116, 2019). "Furthermore, EGFR family of receptors is expressed in neuroblastoma cell lines and tumors where they promote tumor growth and MYCN induction." (PMID 31293052, 2019). "Our study also identified several enriched pathways and gene signatures specific to EμMyc/Casp2−/− or Th-MYCN/Casp2−/− tumors that may be associated with enhanced EμMyc-induced lymphomas and/or delayed Th-MYCN-mediated neuroblastoma." (PMID 30670683, 2019). "Neuroblastoma is a brain tumor; therefore, we speculate that PRPS1 works closely with MYCN to regulate cell proliferation in brain tumor neuroblastoma." (PMID 31443513, 2019). "Since the neuroblastoma patients with metastatic disease is stratified in high risk group regardless of MYCN status from the tumor, MYCN test was not performed in those patients." (PMID 31619207, 2019). "However, the analyses of the Seeger dataset with 102 patients with non-MYCN amplified neuroblastoma using the R2 platform showed unfavorable prognosis in patients with low PRMT1 expression levels." (PMID 30741995, 2019). "Although fluorescence in situ hybridization (FISH) remains the gold standard for clinical diagnosis of MYCN status in neuroblastoma, its limitations warrant the identification of rapid, reliable, less technically challenging, and inexpensive alternate approaches." (PMID 30691436, 2019). "Since most neuroblastoma patients had metastatic disease at the time of diagnosis and were automatically stratified as high risk patients regardless of MYCN status, MYCN tests were not then performed on those patients." (PMID 31619207, 2019). "Furthermore, MYC has also been identified as an independent prognostic marker for poor survival in neuroblastoma and is predominantly expressed by non-MYCN-amplified tumors." (PMID 30744170, 2019). "Surprisingly, all well-known associated factors for high risk neuroblastoma including patient’s age, grade of tumor differentiation, MYCN status and Shimada histology did not significantly affect induction response." (PMID 31619207, 2019).
neuroblastoma (continued). "The tumor proto-oncogene MYCN is an important oncogene in the pathogenesis of neuroblastoma." (PMID 31443513, 2019). "In addition, our data demonstrate that JMJD6 overexpression in neuroblastoma tissues predicts poor patient prognosis, independently of other prognostic markers such as MYCN amplification status, age at the time of diagnosis, and disease stage." (PMID 31346162, 2019). "The type of ALK-expressing tumor (ALCL, IMT, NSCLC, neuroblastoma, melanoma, etc.)and possible concomitant activation of oncogenes, such as MYCN or K-RAS in neuroblastomas, for example, are also determinant for the choice of one particular signaling pathway by tumor cells." (PMID 30813562, 2019). "Thus, the roles of PRMT1 in patients with non-MYCN-amplified neuroblastoma should be further investigated." (PMID 30741995, 2019). "Data from both the Kocak and SEQC-RPM datasets revealed that high expression of survivin was associated with poor overall survival of neuroblastoma patients with non-amplified MYCN, but not of those with amplified MYCN." (PMID 30609639, 2019). "Also, the tumor penetrance in dbh: ALKF1174F mice is less efficient with 40% of the mice having neuroblastoma at 50 weeks of age, compared to Th-MYCN transgenic mice." (PMID 30760980, 2019). "Moreover, BMI1 was shown to cooperate with MYCN in the transformation of benign S-type neuroblastoma cells." (PMID 31856871, 2019). "However, we found that the PRMT1 expression levels were not correlated with MYCN levels in a cohort of patients with non-MYCN-amplified neuroblastoma." (PMID 30741995, 2019). "We included in the analysis 48 cells of the CLB-BER-LUD cell line, another neuroblastoma cell line derived from a stage 4 patient with MYCN amplification but no ALK mutation." (PMID 31452835, 2019). "On the contrary, a follow up high-throughput screen of venetoclax in ∼800 solid tumor cancer cell lines demonstrated that only two groups of solid tumor cancers were sensitive: a subset of MYCN-amplified neuroblastomas, and a subset of high BCL-2 expressing SCLCs." (PMID 30234143, 2018). "Indeed, both LY294002 and rapamycin significantly enhanced entinostat-mediated effects on cell viability, suggesting that HDAC1–3 inhibitors, but not HDAC8 inhibitors, cooperate with PI3K/mTOR inhibitors in our neuroblastoma MYCN-driven model." (PMID 29515255, 2018). "However, approximately half of aggressive neuroblastomas lack MYCN amplification and 30% of neuroblastomas with increased MYCN or C-MYC expression show poor survival." (PMID 30237861, 2018). "Thus, although neuroblastoma cells are more sensitive to TH34 than cell lines of other tumor entities, even neuroblastoma cells show diverse responses, possibly related to different MYCN expression levels (amplification versus single copy)." (PMID 29947893, 2018). "As a result, TFAP4 may play additional oncogenic roles in MYCN-amplified neuroblastoma tumorigenesis." (PMID 29880876, 2018). "MYCMI-6 (12.5 μM) dramatically increased cell death and reduced cell number in MYCN-amplified SK-N-DZ neuroblastoma cells after 24 hours treatment but had only marginal effects on the number of viable cells and the percentage of dead cells in normal lung (IMR-90) and foreskin (BJ) human fibroblasts." (PMID 29968736, 2018). "Additionally, we show that the small molecule inhibitor of eIF4A rocaglamide A (RocA) demonstrates selectivity towards MYCN over-expressing cells, making eIF4A a novel target for neuroblastoma treatment." (PMID 29954071, 2018). "MYCN gene is a well-established prognostic marker in neuroblastoma." (PMID 30621745, 2018). "We demonstrate that LF3000-mediated delivery of BLF1into cells selectively induces apoptosis in MYCN-amplified neuroblastoma cell lines and preferentially down-regulates the translation of eIF4A dependent proteins (as has been seen with small molecule inhibitors of eIF4A)." (PMID 29954071, 2018).
neuroblastoma (continued). "Moreover, MYCN exerts an epigenetic influence in neuroblastoma via several mechanisms involving DNA and histone methylation, and deacetylation." (PMID 29515779, 2018). "Thus, TFAP4 is an attractive therapeutic target, as it is both synthetically lethal and a master regulator for MYCN-amplified neuroblastoma." (PMID 29880876, 2018). "MYCN-specific siRNA was not used, because mouse neuroblastoma cells express low basal levels of MYCN.Neuroblastoma cells were transfected for 72 h with negative control siRNA, siRNA-HADC8, siRNA-c-MYC, or siRNA-HDAC8 + siRNA-c-MYC." (PMID 30237861, 2018). "Aurora A kinase has been shown to stabilise MYCN and early results in preclinical models have proven promising with data suggesting that MLN8237 might reduce MYCN protein levels, decrease cell proliferation and increase differentiation of Neuroblastoma cells." (PMID 29301505, 2018). "Our findings suggest a targeted benefit of LSD1 inhibition in MYCN driven neuroblastoma." (PMID 29515779, 2018). "Several researchers have reported on the role of MYCN in the progression of other tumors including neuroblastoma, and the development of new therapies targeting MYCN could be very attractive." (PMID 30486290, 2018). "MDM2 haploinsufficiency inhibits tumor formation in a MYCN-driven neuroblastoma mouse model." (PMID 29416773, 2018). "In this work, the authors showed a correlation between HDAC8 expression and the International Neuroblastoma Staging System (INSS) stages, as well as with the Shimada pathology classification among others, but they were unable to report an association with MYCN amplification status." (PMID 30344930, 2018). "In addition, MYCN amplification, which is involved in the inhibition of both cell-cycle exit and normal differentiation, contributes to neuroblastoma initiation and progression." (PMID 29678897, 2018). "A connection between ALK and MYC has been observed in neuroblastoma, where ALK gain-of-function mutations are more frequent in MYCN amplified tumors and activation of full length ALK increases mRNA, protein expression, and transformation potential of MYCN in neuroblastoma cell lines." (PMID 29507657, 2018). "The paradigmatic mechanism for disrupted differentiation in neuroblastoma is contingent on amplification of the MYCN proto-oncogene, with high levels of MYCN protein leading to direct repression of genes necessary for terminal differentiation in the sympathetic nervous system." (PMID 29505958, 2018). "Thus, the direct miR-193b target MYCN is insufficiently counteracted by low endogenous miR-193b expression levels in neuroblastoma." (PMID 29719597, 2018). "However, Gal-3 can also exert autocrine effects in neuroblastoma cells by increasing phenotypic differentiation and by impairing MYCN-primed apoptosis via modulation of HIPK2." (PMID 29498681, 2018). "Thus, we combined evidence from VIPER-based predictions of MYCN-amplified neuroblastoma MRs with a whole-genome shRNA screen." (PMID 29880876, 2018). "Finally, we investigated the effect of a combined inhibition of HDAC6, 8 and 10 in short-term cultures of primary neuroblastoma cells isolated from a MYCN-amplified INSS stage 4 tumor of a 1-month-old patient (NB8)." (PMID 29947893, 2018). "MYCN, an oncogenic driver in neuroblastoma, controls pluripotency genes including LIN28B." (PMID 30504901, 2018).
neuroblastoma (continued). "The selective cytotoxic effects of BLF1 and RocA observed in MYCN-expressing SHEP-21N cells suggests that future immunotoxins and eIF4A small molecule inhibitors have potential as future therapeutics in the treatment of neuroblastomas exhibiting MYCN amplification." (PMID 29954071, 2018). "In addition, EZH2 was found to be expressed in high levels in MYCN-amplified neuroblastomas, with MYCN binding at the EZH2 promoter, directly driving expression." (PMID 30326621, 2018). "Children’s Oncology Group (COG) has established the risk stratification system relying on five characteristics: International Neuroblastoma Staging System (INSS) stage, patient age at diagnosis, MYCN gene status, DNA index, and International Neuroblastoma Pathology Classification (INPC)." (PMID 30245940, 2018). "Specifically, the hypothesis was that the development of MYCN-amplification in neuroblastoma cells and these loci would be different than those that predisposed patients to MYCN-nonamplified high-risk neuroblastoma." (PMID 30200332, 2018). "To this end, we reanalyzed data of several in vitro MYCN neuroblastoma model systems." (PMID 30504901, 2018). "Therefore, we further investigated MYCN controlled regulation of the FOXM1 gene signature in neuroblastoma context." (PMID 30504901, 2018). "In summary, miR-193b overexpression induces a cell cycle arrest and apoptosis in neuroblastoma by reducing the expression of MYCN, cyclin D1 and MCL-1, three important oncogenes in neuroblastoma whose inhibition by inhibitors have shown promising results in preclinical testing." (PMID 29719597, 2018). "Taken together, our results demonstrate that TFAP4 is a key regulator of MYCN-amplified neuroblastoma and may represent a valuable novel therapeutic target." (PMID 29880876, 2018). "Interestingly, lipid was markedly elevated in all MYC and MYCN amplified neuroblastoma and medulloblastoma." (PMID 29541417, 2018). "It is interesting to note that MYC protein overexpression was associated with around 30% of High MKI neuroblastomas without MYCN amplification." (PMID 29464082, 2018). "Here, by integrating evidence from a whole-genome shRNA library screen and the computational inference of master regulator proteins, we identify transcription factor activating protein 4 (TFAP4) as a critical effector of MYCN amplification in neuroblastoma, providing a novel synthetic lethal target." (PMID 29880876, 2018). "The large dynamic range of scores in neuroblastoma tumors warranted us to evaluate whether this heterogeneous expression pattern could reflect tumor characteristics including MYCN status and patient survival." (PMID 30504901, 2018). "About half of neuroblastomas are highly aggressive, as indicated by dissemination in children over one year of age or by adverse biological features such as amplification of the MYCN oncogene and by unresponsiveness to induction therapy or early relapse if a response is achieved." (PMID 30018737, 2018). "Although SNAIL and CDH1 were not identified in our RNAseq analysis, it is possible that TFAP4 regulates a different set of EMT effectors and may restrict differentiation of MYCN-amplified neuroblastoma by this mechanism as well." (PMID 29880876, 2018). "Driver genes/alterations, such as MYCN, 1p/11q deletion, ALK, ATRX and TERT, are characterized in high-risk neuroblastoma by previous studies, however, it is difficult to further stratify the high-risk neuroblastoma at molecular level." (PMID 30405689, 2018).
neuroblastoma (continued). "Since we noticed that high MRE11 expression occurs in MNA neuroblastoma, we speculated that MRE11 function might be required to control MYCN-associated RS and DNA damage, in this tumor subset." (PMID 30166519, 2018). "IGF2BP1 clearly influenced MYCN expression and neuroblastoma cell survival." (PMID 29954406, 2018). "Intriguingly, MRE11 is highly expressed and predicts bad prognosis in MYCN-amplified neuroblastoma." (PMID 30166519, 2018). "The MYCN driven murine neuroblastoma tumors all harbor additional genomic alterations." (PMID 29492199, 2018). "In fact, MYCN is one of the best characterized genetic alterations in neuroblastoma; and copy number gain of chromosome 17q, where OTOP3 is located, is a known neuroblastoma risk factor." (PMID 30012197, 2018). "Based on these results, we conclude that the observed anti-proliferative effect of miR-193b in neuroblastoma is mediated, at least in part, through targeting both cyclin D1 and MYCN, two oncogenes with essential roles in neuroblastoma tumorigenesis and thereby attractive therapeutic targets." (PMID 29719597, 2018). "Although validated in MYCN-driven neuroblastoma cell lines, BLF1 may also be of use in more common c-Myc-driven tumours, as has been seen with small molecule inhibitors of eIF4A." (PMID 29954071, 2018). "Interestingly, specific CDK2 inhibition is found to be synthetically lethal to MYCN-driven neuroblastoma suggesting a potential role for CDK2-inhibiting drugs also in MB-carrying amplifications in MYCN and perhaps also MYC." (PMID 29511348, 2018). "However, these indicators only cover a portion of all neuroblastoma cases (ca. 22% of all neuroblastoma tumors present MYCN amplification)." (PMID 29615097, 2018). "The MYCN oncogene plays a critical role in neuroblastoma tumorigenesis." (PMID 30237861, 2018). "Approximately 50% of high-risk patients have MYCN-amplified tumors, and while all tumors classified as high-risk are clinically aggressive, it is well known that the biology of MYCN-amplified and MYCN-nonamplified high-risk neuroblastoma are disparate." (PMID 30200332, 2018). "Likewise, the combined ALKF1174L and MYCN targeted overexpression can be sufficient as the sole two genetic events to drive neuroblastoma formation while a higher number of alterations are observed in the ALKF1174L driven cases." (PMID 29492199, 2018). "MYCN amplification occurs in approximately 45% of primary high-risk neuroblastomas and is the strongest independent negative prognostic risk factor in patients." (PMID 29416773, 2018). "Regardless, these observations indicate that a phenotypic range of neuroblastoma cells are susceptible to Zika virus infection, independent of MYCN amplification." (PMID 30044847, 2018). "In this study, we evaluate the effect of LSD1 inhibition with HCI-2509 in poorly differentiated neuroblastoma cell lines and examine the global transcriptomic changes induced by HCI-2509 to elucidate the mechanisms of the efficacy of HCI-2509 in MYCN amplified neuroblastoma cells." (PMID 29515779, 2018). "Additionally, BET inhibition has most recently been shown to be a potential novel therapeutic strategy for MYC-amplified MB patients and MYCN-amplified neuroblastoma patients." (PMID 29511348, 2018). "A number of studies have demonstrated that miRNAs are differentially expressed between high-risk and low-risk neuroblastomas, and also between MYCN-amplified and non-MYCN-amplified neuroblastomas." (PMID 29719597, 2018).